EGR1 (early growth response 1)
Diseases named in the same sentence as EGR1 in open-access papers (continued):
Sharing a sentence is not in itself a finding about the gene and the disease.
infection (continued). "Notably, an increase in GTP-bound (active) forms of RhoA, Rac1 and Cdc42 was observed in WT cells after 1 h of infection; however, such activation was largely prevented in Egr-1-knockout cells." (PMID 38233877, 2024). "Therefore, we explored the possible relationship between Egr-1 activity and cytoskeleton alteration during infection." (PMID 38233877, 2024). "However, this increased EGR1 expression was significantly greater at 2 and 4 h post-infection with BWP17+cIP30." (PMID 39635778, 2024). "Notably, infection with SC5314 induced a higher expression of Egr1 (pAdj = 0.0502) at 9 h post-infection." (PMID 39635778, 2024). "Moreover, immunofluorescence analysis was performed to examine the distribution and expression of ZO-1, Occludin, and Claudin-5 in Egr-1−/− and WT hBMEC upon infection." (PMID 38233877, 2024). "To further determine the effects of Egr-1 on CNS inflammation induced by meningitic E. coli, we subsequently assessed its ability to regulate cytokine and chemokine production in response to in vivo infection using electrochemiluminescence assay." (PMID 38233877, 2024). "By isolating the brain microvessels from the bacterium-challenged and control mice, we found that the transcriptional level of Egr-1 mRNA in mouse brain microvessels was significantly upregulated, with a greater than 40-fold increase at the early stage of infection." (PMID 38233877, 2024). "After infection, the EGR1 upregulation was observed via the MAPK-ERK pathway." (PMID 36844409, 2023). "Finally, EGR1 was dramatically upregulated (~70-fold over mock) in response to infection with RVFV, a phlebovirus known to induce major damage to the CNS." (PMID 35746681, 2022). "Among IEGs, EGR1 was the most differentially regulated IEG upon infection with P. aeruginosa." (PMID 35508983, 2022). "Thus, antagonizing the EGFR/EGR1 signaling enables CMV to maintain a productive infection and suggests EGR1 serves a pro-viral role during CMV infections." (PMID 36338037, 2022). "Taken together, these data support the model that the combined actions of VopQ and VopS create a pulse of ERK1/2 MAPK signaling that is restricted to early infection time points, resulting in the controlled expression of downstream transcription factors EGR1 and FOS." (PMID 33563785, 2021). "Similar to HSV-1, the HCMV major immediate early proteins can activate the TGFβ promoter, which occurs indirectly through IE2 transactivation of the cellular immediate early transcription factor EGR-1, but was also shown to require additional viral factors during infection." (PMID 34411201, 2021). "The RNA levels of FOS, and EGR1 were significantly increased as early as 1-day post-infection." (PMID 34545078, 2021). "This may explain the increased expression (and thus enrichment) of Egr-1 in tandem with a heightened immune response observed clinically as a severe (PEDIS 4) infection." (PMID 33753735, 2021). "Because Egr-1 is an important mediator and regulator of inflammatory responses to extracellular stimuli, we investigated whether intracellular signaling in an infection model could also mediate Egr-1 responses." (PMID 31681626, 2019). "CMV miR-US22 targets EGR1 in the context of infection in CD34+ HPCs." (PMID 31725811, 2019). "Finally, CMV replication in fibroblasts stimulates WT1 expression, which competes antagonistically for EGR1 targets, including EGFR, and indicates another mechanism by which the virus antagonizes EGFR/EGR1 signaling for productive infection." (PMID 31725811, 2019). "In order to determine the effect of the miR-US22 mutation on EGR-1 expression, western blot analysis of EGR-1 was performed on HCMV WT and ΔmiR-US22 TB40E infected NHDF or aortic endothelial cells (AEC) at 2, 3, 4 and 6 days post infection (dpi)." (PMID 31725809, 2019). "However, this factor appears to play a distinct role during the infections of these two Orthopoxviruses as depletion of EGR-1 by siRNA solely affects VACV replication." (PMID 29561772, 2018).
infection (continued). "EGR1 protein expression was also gradually upregulated as the infection progressed." (PMID 30319594, 2018). "Thus, the factor or factors responsible for EGR1’s upregulation upon infection appear to include both MYR1-dependent and MYR1-independent factors." (PMID 29615509, 2018). "Different viruses, such as the KSHV (Kaposi’s sarcoma-associated herpesvirus), HSV-1 (herpes simplex virus type-1), JCV (human polyomavirus JC virus), HIV (human immunodeficiency virus) and EBV (Epstein-Barr virus) are also capable of modulating the egr-1 gene function during infection." (PMID 29561772, 2018). "This could possibly be due to the fact that Egr-1 becomes phosphorylated (through membrane fusion and viral replication) during primary de novo infection." (PMID 29207655, 2017). "Moreover, the induction of EGFR and amphiregulin occurred at later time points than that for EGR1, i.e., at 4–6 h post infection." (PMID 28180113, 2017). "Moreover, we also found that depletion of either Egr-1 or CBP leads to a reduction in RTA promoter activity during de novo infection." (PMID 29207655, 2017). "Additionally, we determined the role of Egr-1 in regulating RTA expression during primary de novo infection of KSHV." (PMID 29207655, 2017). "The gastric pathogen H. pylori triggered EGR1 upregulation at 2 h after infection, whereas the non-pathogenic gastric isolate L. rhamnosus did not." (PMID 28180113, 2017). "Furthermore, the strongest response is observed in cells originating from the natural site of the infection, suggesting that the EGR1 induction is cell type specific." (PMID 28180113, 2017). "EGR1−/− MEFs demonstrated lower levels of susceptibility to VEEV-induced cell death than wild-type MEFs, indicating that EGR1 modulates proapoptotic pathways following infection." (PMID 26792742, 2016). "Interestingly, we found further that the expression of EGR1, one member of EGRs family was rapidly up-regulated following infection by A. fumigatus conidia into A549 cells." (PMID 26273834, 2015). "We showed that Egr-1 transcript can be detected an hour after infection." (PMID 25264522, 2013). "Collectively these results demonstrated that Egr-1 induced by infection may be recruited to HSV-1 key sequences and potentially has regulatory effects on viral gene expression and replication." (PMID 25264522, 2013). "However, at 1 day post-infection, Egr1 and En1 were identified as enriched transcription factor binding sites in genes downregulated in WT mice, but not KO mice." (PMID 22713837, 2012). "Several different viruses are known to activate Egr-1 expression upon infection." (PMID 22428032, 2012). "Therefore, it was necessary to determine the expression pattern of cellular egr-1 and virus-encoded ORF50 during both early stages of infection as well as during virus reactivation (late stages)." (PMID 22428032, 2012). "As expected, Egr1 expression had declined by 3 h and further by 6 h of infection." (PMID 23248776, 2012). "Interestingly, results showed that Egr-1 mRNA was produced as early as 1 hour post infection and a higher concentration of Egr-1 mRNA was observed 3 hours post infection." (PMID 21619646, 2011). "RT-PCR assays were used to analyze Egr-1 mRNA transcript expression upon infection." (PMID 21619646, 2011). "While Egr1 mRNA abundance peaked at 60 min and returned to baseline levels by 120 min, the increase in protein abundance measured by immunoblotting was, as expected, offset from the increase in mRNA, peaking at 120 min post infection and returning to undetectable levels by 240 min." (PMID 41188240, 2025). "However, only EGR1 showed significant increases in protein levels in infected cells with significantly elevated protein levels at 2 h (2.2-fold; p < 0.01) and 4 h (2.3-fold; p < 0.01) post-infection." (PMID 39635778, 2024). "However, both heat-killed and live S. Typhimurium were able to induce EGR1 at 2 h post infection." (PMID 28180113, 2017).
infection (continued). "Therefore, Egr-1 actively regulates RTA transcription during primary de novo infection." (PMID 29207655, 2017). "Next, we verified whether active infection was responsible for Egr-1 phosphorylation by infecting them with an UV inactivated virus (UV), which showed a significantly reduced level of Egr-1 as compared to the cells infected with the live virus (a for THP-1 and d for HUVECs)." (PMID 29207655, 2017). "Since the expression and phosphorylation of Egr-1 is one of the key factors in regulating viral reactivation, we wanted to determine whether Egr-1 gets phosphorylated during the initial burst of lytic cycle during de novo infection." (PMID 29207655, 2017). "We also examined EGR1 expression in BMDMs from C57BL/6J mice, and showed that SFTSV infection upregulated EGR1 expression." (PMID 40789964, 2025). "Following this, the role of EGR1 in the inflammatory response was further assessed by measuring the level of IL-1β produced by EGR1KO and EGR1WT macrophages during infection." (PMID 41188240, 2025). "The Egr-1−/− mice were used to evaluate the contribution of Egr-1 to VEGFA, PDGFB, and ANGPTL4 production in response to the infection." (PMID 38233877, 2024). "We identified that T3SS and T6SS affect EGR1 and FOS genes expression in type II pneumocytes during infection." (PMID 35508983, 2022). "Infection with vaccinia virus (VACV), a member of the Poxviridae family, induces MAPK pathway activation which subsequently activates EGR1." (PMID 36338037, 2022). "We determined that T3SS and T6SS modulate the expression of EGR1, FOS, and numerous genes that are involved in proinflammatory responses in epithelial cells during infection." (PMID 35508983, 2022). "After 2 h of infection, the transcriptional upstream regulators EGFR, EGR1, FOXL2, FOXO3, IL1A, IL1B and RELA were activated in MKN-28 cells infected with either H. pylori wt or the ΔhtrA mutant, while WWTR1 was inhibited." (PMID 37193047, 2022). "To address this question, we generated 293T and HeLa cell lines stably expressing both FLNA shRNA and EGR1 shRNA using the cell line expressing FLNA shRNA and a lentiviral infection system." (PMID 35563324, 2022). "During infection with the T6SS mutant, the expression of the FOS and EGR1 genes increased in epithelial cells compared to infection with the parental strain." (PMID 35508983, 2022). "Since UL138 acts to maintain EGFR surface levels and MEK/ERK signaling, a feed-forward loop of EGR1 expression, UL138 expression, and EGFR surface levels is established during infection." (PMID 32759334, 2020). "Surprisingly, despite the widespread infection with the virus, changes in the transcriptome remained limited to only a few genes: GALR3, EGR1, E2F2, RNY4, DBX2 were found upregulated, and ITM2C was downregulated." (PMID 33490061, 2020). "The reduced responsiveness of EGR1 to EGF stimulation in infected cells likely reflects diminished EGFR levels and signaling in the context of infection beginning at 24 hpi." (PMID 31725811, 2019). "From this work, a model emerges whereby high levels of EGR1 in CD34+ HPCs primes these cells for expression of UL138 and the establishment of latency upon infection." (PMID 31725811, 2019). "Both wildtype and SAP mutant FMDV infection resulted in EGR1 upregulation, however, SAP mutant FMDV resulted in a higher upregulation of EGR1." (PMID 30319594, 2018). "Taken together, our findings reveal that both Egr-1 and CBP are involved in the regulation of RTA promoter activity during de novo primary infection." (PMID 29207655, 2017). "The infection of HUVECs and THP-1 with KSHV showed augmented Egr-1 phosphorylation when compared with the respective mock infected (M) cells (a for THP-1 and d for HUVECs)." (PMID 29207655, 2017). "EGR1 mRNA and protein levels, and HTLV-1 Tax protein levels were upregulated in both cell lines, indicating that early infection also induced EGR1 expression." (PMID 28881635, 2017).
infection (continued). "The expression levels of Egr-1 and respective GAPDH at different time points (2, 6, 12 and 24h) post-infection are shown in THP-1 and HUVECs transfected with either pA3F-Egr-1 or pA3F (empty vector) (c for THP-1 and 7B, c for HUVECs)." (PMID 29207655, 2017). "Our data demonstrate that both Egr-1 and CBP are involved in regulating RTA promoter activity during KSHV primary infection." (PMID 29207655, 2017). "We also validated the correlation between Egr-1 expression and RTA transcription during primary infection by infecting the Egr-1 depleted cells with KSHV." (PMID 29207655, 2017). "We have studied the role of Egr-1 and CBP in regulating RTA promoter activity during primary infection." (PMID 29207655, 2017). "We further confirmed the significance of Egr-1 expression on RTA transcription during KSHV primary infection by infecting THP-1 and HUVECs overexpressing Egr-1." (PMID 29207655, 2017). "Inhibition of c-KIT with OSI930 fully restored EGR1 levels in cells infected with virulent Y. enterocolitica and significantly recovered transcription of IL-8 and CCL20 at 5 h and 20 h post-infection (dark grey bars)." (PMID 24206648, 2013). "Expression of Egr-1 and RTA proteins were significantly elevated by 1 hour post infection (hPI) and continued to maintain increased expression until roughly 6–8 hPI (lanes 2–4)." (PMID 22428032, 2012). "Taken together, the expression profiles of Egr-1 and RTA seem to follow an identical pattern during primary infection of cells." (PMID 22428032, 2012). "Since BCBL-1 cells already carry KSHV DNA, KSHV-infected HEK293 cells were used to evaluate the expression pattern of Egr-1 and KSHV RTA during early stages of de novo infection." (PMID 22428032, 2012). "In the present study, we demonstrate for the first time that Egr-1 protein is induced rapidly in cells such as SIRC and VERO upon infection." (PMID 21619646, 2011). "In addition, gene ontology enrichment analysis also revealed significant upregulation of known pro cell-death genes in infection of the EGR1KO macrophages, consistent with a role of EGR1 in limiting macrophage death." (PMID 41188240, 2025). "The absence of EGR1 protein 240 min post infection indicates a short half-life of EGR1 protein and that its biological effect is likely rapid." (PMID 41188240, 2025). "In contrast, the Egr1 expression in cells infected with the injectisome mutant were not much greater at 60 min post infection than in mock-infected cells." (PMID 41188240, 2025). "This suggests that the production of EGR1 in the early stages of infection is not dependent on fungal morphology." (PMID 39635778, 2024). "As such, EGR1 likely plays a role in host homoeostasis by driving a priming response to better respond to a possible invasive infection, rather than inciting a proinflammatory response." (PMID 39635778, 2024). "Although the downregulation of TJ proteins upon infection was not completely abolished, a significantly attenuated decrease in TJ proteins at both mRNA and protein levels in Egr-1-knockout hBMEC was observed compared with those in control hBMEC." (PMID 38233877, 2024). "Although zymosan is a ligand of Dectin-1, the inhibition of Dectin-1 did not significantly alter the levels of EGR1 during treatment with zymosan, or during infection with C. albicans." (PMID 39635778, 2024). "Infection of OECs treated with EGR1 siRNA for 24 h had no impact on fungal-induced OEC cellular damage as measured by lactate dehydrogenase (LDH) release." (PMID 39635778, 2024). "Critically, targets of transcription factors known to regulate inflammation (IRF1, STAT1, STAT3) and fibrosis (SMAD2/3, EGR1, TEAD4, YAP1) appeared to be highly induced in the host, consistent with prior reports of infection-dependent induction of pro-inflammatory and pro-fibrotic gene expression." (PMID 36923592, 2023). "EGR1 was found to be activated irrespective of IFN-β treatment following infection with foot and mouth disease virus (FMDV) in PK-15 and HEK-293 T cells." (PMID 36338037, 2022).
infection (continued). "Three promising genes (EGR1, JUN and FOS) were eventually identified, and were significantly and differentially expressed in the same breed under different conditions, and in the two breeds after ST infection." (PMID 36557693, 2022). "To determine whether RhoA participates in the regulation of Pol-III-directed transcription mediated by EGR1, we generated 293T and HepG2 cell lines stably expressing both EGR1 shRNA and RhoA–EGFP, using a lentiviral infection system." (PMID 35563324, 2022). "Clear host transcriptional responses could be observed 8 h after infection, including the documented MAPK-based activation of FOS, EGR1, and c-JUN gene expression, in both parental and uS10-KI cells." (PMID 33912921, 2021). "We repeated the infection time course with the V. parahaemolyticus T3SS1+ΔvopQ strain and found that the T3SS1-induced pulse of ERK1/2 phosphorylation was indeed dependent on VopQ, as was the increase in total Egr1 protein levels." (PMID 33563785, 2021). "The EGR1 antibody precipitated sequences in the wild-type infection for both binding sites by PCR; but not in the NC or IgG control." (PMID 31725811, 2019). "We therefore used EGR1 upregulation as a marker for EGFR activation and examined whether T4SS or CagL is involved in the activation of EGFR during infection." (PMID 29468142, 2018). "Knockdown of EGR1 and c-FOS by siRNA transfection suppressed macrophage autophagy before and after PA infection; while overexpression of these two transcription factors enhanced autophagy but reversed the role of BD2 and BD3 on macrophage-mediated PA eradication." (PMID 29487594, 2018). "Furthermore, de novo infection of THP-1 (monocytic) and HUVECs (endothelial) cells showed an upregulation of Egr-1 phosphorylation, whereas depletion of Egr-1 reduced the mRNA levels of RTA during primary infection." (PMID 29207655, 2017). "In contrast, EGR1−/− cells showed little to no detectable caspase cleavage following infection with VEEV." (PMID 26792742, 2016). "The results showed that the cells while infected with A4 exhibited a 26-fold increase of Egr-1 expression whereas the recombinant virus A7 generated a 130-fold increase compared to no infection control." (PMID 25346859, 2014). "We also show that ~95% depletion of c-KIT transcript levels by siRNA treatment rescued EGR1, VCAM1, CCL20, and IL-8 gene expression in response to Y. enterocolitica WA infection in THP-1 cells, compared to infected control cells treated with non-targeting siRNA (si-CTL)." (PMID 24206648, 2013). "HeLa cells were transfected with an Egr-1-luciferase vector with or without FOXO3a siRNA for 24 hours, followed by infection with Ad-TatSF2." (PMID 20862322, 2010). "Taken together, these results suggest that the trigger for Egr1 upregulation occurs very rapidly during infection and does not require transport of effectors into the host cell but rather is likely a result of injectisome penetration of the macrophage plasmalemma." (PMID 41188240, 2025). "Furthermore, the key role we identified for NF-κB signalling in inducing EGR1 production shows that EGR1 is regulated by general fungal recognition, rather than invasive infection." (PMID 39635778, 2024). "Notably, a recent study has identified a role for EGR1 in anti-SARS-CoV2 responses, demonstrating that this transcription factor potentially plays a hiterhto unsuspected role in the body’s immune responses to infections." (PMID 39635778, 2024). "In addition, infection with wild-type C. burnetii, but not with the ΔankG mutant resulted in down-regulation of EGR1." (PMID 35134097, 2022). "These master regulators include EGR1, FOS, SRF, and SP1, and could be interesting targets for future studies, since they could switch on several pathways targeting the genes that are important to the successful alleviation of HPAI infection." (PMID 35205087, 2022).